HMGA2 (high mobility group AT-hook 2)
Diseases named in the same sentence as HMGA2 in open-access papers (continued):
Sharing a sentence is not in itself a finding about the gene and the disease.
thyroid cancer (continued). "We validated the downregulation of SNAI2, SOX4, and TGFBR2, three targets never investigated in thyroid cancer cells, and of HMGA2, a miR-2 04-5p target previously identified in the lab (unpublished results), in TPC-1 and BCPAP cells following miR-204-5p overexpression." (PMID 37445942, 2023).
bladder cancer (20 papers, 2015 to 2025). "Studies have shown high tissue levels of HMGA2 protein and its association with clinicopathological characteristics in various cancers, including breast, liver, gastric, and bladder cancer." (PMID 40853523, 2025). "Based on these findings, the detection of HMGA2 in tissue samples can be used as a supporting diagnostic marker for bladder cancer, aiding in the determination of its stage, grade, and muscle invasion status." (PMID 40853523, 2025). "Gstt2, Gphn, Plec Cmss1, Ahnak, Slc2a1, Gsta4, Kras, Peak1, and Hmga2 were associated with worse overall survival in bladder cancer patients, and the association was significant for Gstt2 and Ahnak." (PMID 39769061, 2024). "Ankfn1, Gstt2, Plec, Gphn, Fmo5, Cmss1, Ahnak, Mecom, Slc2a1, Gsta4, Kras, Peak1, and Hmga2 were associated with worse disease-free survival in bladder cancer patients." (PMID 39769061, 2024). "For example, HMGA2 was found to be associated with epithelial-to-mesenchymal transition in bladder cancer, and SKIP was reported to be associated with histological grades and poor prognosis." (PMID 28977887, 2017). "H-Ras and HMGA2 are of particular interest because expression of these molecules is elevated in bladder cancer patients, and elevated H-Ras expression has been linked to worse patient outcome." (PMID 27382433, 2016). "A recent study showed that expression of HMGA2, loss of E-cadherin, and expression of vimentin are significantly correlated with bladder cancer grade and stage." (PMID 26640315, 2015). "Therefore, this study aimed to investigate the presence and levels of HMGA2 protein in the plasma of bladder cancer patients and its association with stage, grade, and muscle invasion." (PMID 40204943, 2025). "Additionally, higher HMGA2 protein levels were associated with higher bladder cancer grade (p < 0.05)." (PMID 40853523, 2025). "However, further studies involving larger patient cohorts with various types and stages of bladder cancer are needed to confirm the significance of HMGA2 protein levels in the diagnostic approach for bladder cancer." (PMID 40853523, 2025). "The immunohistochemical staining results demonstrated a statistically significant correlation between elevated HMGA2 protein levels and the progression of bladder cancer stages in the patients (p < 0.05)." (PMID 40853523, 2025). "In this context, many histological studies were conducted to investigate the relationship between HMGA2 protein expression levels and histological and clinical characteristics of bladder cancer tissues, and compared them with normal adjacent tissues." (PMID 40204943, 2025). "In this study, we confirmed that the plasma HMGA2 protein level elevated in patients with bladder cancer and that the plasma HMGA2 protein level was higher in patients with MIBC than in patients with NMIBC." (PMID 40204943, 2025). "Increased expression of caspase 1 was observed in bladder cancer cells, as well as the prevalence of pyroptosis, which suggested the secretion of HMGA2 in the plasma of bladder cancer patients." (PMID 40204943, 2025). "Accordingly, plasma HMGA2 protein levels can be used as a potential non-invasive marker for managing bladder cancer." (PMID 40204943, 2025). "HMGA2 protein is overexpressed in bladder cancer tissues and correlates with tumor progression and aggressiveness." (PMID 40853523, 2025). "The present study demonstrated that HMGA2 protein is overexpressed in bladder cancer tissues compared to adjacent normal tissues, with levels positively correlated with tumor stage, grade, and muscle invasion." (PMID 40853523, 2025). "An 11-gene signature (Hmga2, Peak 1, Kras, Slc2a1, Ankfn1, Ahnak, Cmss1, Fmo5, Gphn, Plec, Gstt2) had the most substantial impact on disease-free survival in bladder cancer patients." (PMID 39769061, 2024). "In bladder cancer, upregulation of HMGA2 leads to EMT induction, which enhances the progression of tumor cells." (PMID 38733529, 2024).
bladder cancer (continued). "This study suggests that the upregulation of miR‐let‐7c‐5p inhibits bladder cancer progression by targeting HMGA2 protein." (PMID 36545841, 2023). "In bladder cancer, the expression of miR‐let‐7c‐5p is reported to be downregulated, thus increasing HMGA2 expression significantly." (PMID 36545841, 2023). "HMGA2 can be considered a promising marker for bladder cancer." (PMID 40853523, 2025). "In the context of bladder cancer, two significant histological studies have explored the relationship between HMGA2 protein expression levels and the histological and clinical characteristics of bladder cancer, comparing these levels with those in adjacent normal tissues." (PMID 40853523, 2025). "Consequently, HMGA2 protein can be considered a possible marker for the incidence and progression of bladder cancer." (PMID 40853523, 2025). "Thus, the plasma HMGA2 concentration represents a potential non-invasive marker for bladder cancer diagnosis and management." (PMID 40204943, 2025). "Notably, circ-0000658 promotes the expression level of HMGA2 via miR-498 inhibition to facilitate tumorigenesis in bladder cancer." (PMID 38733529, 2024). "Moreover, miR-152-3p was found to target high mobility histone A2 (HMGA2), further inhibiting bladder cancer cell proliferation and invasion by suppressing HMGA2 expression." (PMID 39606232, 2024). "Our analysis revealed a network of TFs whose activity could be essential to Basal bladder cancer biology, including HMGA2, KLF7, NR3C1 and ZBED2." (PMID 36944729, 2023). "For example, miR-485-5p has been recognized as a tumor suppressor, and its ectopic expression could restrict EMT and metastasis of bladder cancer cells through targeting HMGA2." (PMID 35031054, 2022). "Studies showed that circ_0000658 was highly upregulated in bladder cancer; nevertheless, circ_0000658 knockdown reduced the EMT phenotypes by regulating the miR-498/HMGA2 pathway." (PMID 38361784, 2024). "In-depth probing discloses that LINC00355 up-regulates HMGA2 by sponging miR-424-5p, thereby heightening migration, invasion, and EMT of bladder cancer cells and facilitating lung metastasis of xenograft tumors." (PMID 37827696, 2023). "Immunohistochemical staining revealed that 70% (28/40) of bladder cancer tissue samples exhibited high levels of HMGA2 protein, whereas no HMGA2 protein was detected in the 20 normal bladder tissue samples." (PMID 40853523, 2025). "This study showed that HMGA2 protein was overexpressed in 70% of bladder cancer tissues, with no expression in normal tissues." (PMID 40853523, 2025). "An increasing body of evidence has shown that HMGA2 is overexpressed in most tumor tissues or cancers, except for GC, NSCLC, CRC, BC, and esophageal cancer, also including thyroid cancer, bladder cancer, endometrial cancer, cervical cancer, tongue cancer, and kidney cancer." (PMID 38361784, 2024). "Many protein coding genes from the newly identified ceRNA network were reported as oncogenes and/or tumor suppressors participating in bladder cancer development and progression, such as CDKN1A, HMGA2 and MYC, which also was considered as promising therapeutic targets for bladder cancer." (PMID 27863388, 2016).
nasopharyngeal carcinoma (18 papers, 2015 to 2025). A carcinoma arising from the nasopharyngeal epithelium. "In conclusion, the close association of HMGA2 with the malignant progression, drug resistance, and adverse prognosis of nasopharyngeal carcinoma underscores its potential as a significant malignancy biomarker." (PMID 38304037, 2023). "In summary, although HOXC13-AS exerts oncogenic function by regulating the miR-383-3p/HMGA2 axis, it also provides new ideas for the treatment of nasopharyngeal carcinoma patients to a certain extent." (PMID 39981436, 2025). "For example, knockdown of HMGA2 significantly inhibited EMT in nasopharyngeal carcinoma cell lines by targeting the TGFβ/SMAD3 signaling pathway." (PMID 38361784, 2024). "This suggests that HMGA2 has the potential to become a crucial target for diagnosis, treatment, and prognostic assessment in nasopharyngeal carcinoma." (PMID 38304037, 2023). "This review focuses on elucidating the oncogenic role of HMGA2 in NPC, suggesting its potential association with chemotherapy resistance in NPC, and proposing its candidacy as an independent factor in nasopharyngeal carcinoma prognosis assessment." (PMID 38304037, 2023). "In this review, our emphasis is primarily on highlighting the oncogenic role of HMGA2 in nasopharyngeal carcinoma." (PMID 38304037, 2023). "In the HOXC13-AS/miR-383-3p/HMGA2 axis, the overexpression of HOXC13 antisense RNA (HOXC13-AS) and high mobility group A2 (HMGA2) and the downregulation of miR-383-3p were found in nasopharyngeal carcinoma (NPC) tissues and cells." (PMID 36313570, 2022). "We aimed to investigate the function and mechanism of let-7a in nasopharyngeal carcinoma metastasis and clarified the regulation of high mobility group A2 (HMGA2) by let-7a." (PMID 25884389, 2015). "Moreover, EVs secreted from Epstein–Barr virus-positive nasopharyngeal carcinoma carry high-mobility-group AT-hook 2 (HMGA2) proteins, and stimulate EndMT and vascular endothelial barrier inhibition, therefore promoting metastasis." (PMID 40650130, 2025). "Similarly, HMGA2 has also been shown to influence the process in resistance studies for nasopharyngeal carcinoma." (PMID 38304037, 2023). "In addition, some studies have reported the possibility that HMGA2 is involved in modulating the resistance mechanism of other anti-nasopharyngeal cancer drugs, such as docetaxel, and resistance to targeted therapy drugs." (PMID 38304037, 2023). "HMGA2 exhibits abnormally high expression in nasopharyngeal carcinoma cell lines and tissues." (PMID 38304037, 2023). "HMGA2 promotes the proliferation of nasopharyngeal carcinoma cells by regulating the cell cycle." (PMID 38304037, 2023). "The Function and significance of HMGA2 in nasopharyngeal carcinoma and related mechanisms." (PMID 38304037, 2023). "Additionally, the detailed mechanisms of HMGA2 in conferring resistance in nasopharyngeal carcinoma and its specific regulatory role in tumor stemness pathways remain insufficiently explored, necessitating further in-depth investigation." (PMID 38304037, 2023). "It has been found that HMGA2 is abnormally high in nasopharyngeal carcinoma." (PMID 38304037, 2023). "In summary, HMGA2 is a key regulator of the malignant progression of nasopharyngeal carcinoma." (PMID 38304037, 2023). "Similarly, studies have shown that high expression of HMGA2 is closely related to poor prognosis in patients with nasopharyngeal carcinoma." (PMID 38304037, 2023). "High HMGA2 expression also promotes cell proliferation and invasion in nasopharyngeal carcinoma." (PMID 35388172, 2022). "Consequently, HMGA2 contributes to the malignant progression of nasopharyngeal carcinoma." (PMID 38304037, 2023). "Therefore, HMGA2 has been shown to increase drug resistance in a variety of malignant tumors, including nasopharyngeal carcinoma, thereby affecting the therapeutic effect of tumors, and these research results provide new ideas and targets for anti-drug resistance to malignant tumors." (PMID 38304037, 2023).
nasopharyngeal carcinoma (continued). "Therefore, serum exosome HMGA2 can be used as a promising prognostic biomarker and therapeutic target, thereby providing a better diagnosis and treatment strategy for patients with nasopharyngeal carcinoma." (PMID 38304037, 2023). "Recent studies have increasingly unveiled the critical role of HMGA2 in nasopharyngeal carcinoma (NPC), particularly in promoting malignant progression, correlating with tumor resistance, and serving as an independent adverse prognostic factor." (PMID 38304037, 2023). "In addition, in nasopharyngeal carcinoma, HOXC13 antisense RNA (HOXC13-AS) promoted EMT-induced invasion via regulating the miR-383-3p/HMGA2 pathway." (PMID 38361784, 2024).
pancreatic ductal adenocarcinoma (18 papers, 2015 to 2026). An infiltrating adenocarcinoma that arises from the epithelial cells of the pancreas. "In detail, HMGA2 has been linked to histone acetyl transferase (HAT) expression regulation in pancreatic ductal adenocarcinoma, which is in turn linked to increased levels of H3K9ac and H3K27ac in the fibrotic region." (PMID 31382504, 2019). "Expression of the chromatin-associated protein HMGA2 correlates with progression, metastasis and therapy resistance in pancreatic ductal adenocarcinoma (PDAC)." (PMID 30228296, 2018). "Moreover, analyses of human pancreatic ductal adenocarcinoma (PDAC) tumor tissues detected the association of nuclear Src with the HMGA2 and SMYD3 gene promoters." (PMID 26695438, 2016). "Recently, researchers indicated that H19 inhibited endogenous let-7 function, causing derepression of HMGA2 which could mediate epithelial-mesenchymal transition (EMT) in pancreatic ductal adenocarcinoma (PDAC), and contributed to PDAC metastasis." (PMID 27672656, 2016). "In pancreatic ductal adenocarcinoma (PDAC), nuclear HMGA2 expression is associated with tumor dedifferentiation and presence of lymph node metastasis." (PMID 34302528, 2021). "It is demonstrated that immunoreactivity of HMGA2 is correlated to poor differentiation in pancreatic ductal adenocarcinoma." (PMID 29596435, 2018). "H19 can also promote cell invasion and migration in pancreatic ductal adenocarcinoma, at least partially by increasing HMGA2-mediated epithelial-mesenchymal transition through antagonizing let-7." (PMID 25944697, 2015). "In addition, studies have shown that H19 enhances invasion and migration of pancreatic ductal adenocarcinoma cells by decreasing let-7 and subsequently increasing the HMGA2-mediated epithelial-mesenchymal transition (EMT)." (PMID 30071841, 2018). "H19 could also act as a molecular sponge for let-7, which is a well-known tumor suppressor miRNA capable of targeting and inhibiting oncogenic HMGA2, a mediator of epithelial–mesenchymal transition (EMT) in pancreatic ductal adenocarcinoma (PDAC)." (PMID 33800276, 2021).
pituitary tumor (18 papers, 2006 to 2024). A benign or malignant neoplasm affecting the pituitary gland. "The HMGA2 ability to accelerate the cell cycle by enhancing E2F activity and promoting cyclin B expression is in agreement with former data that have reported the development of pituitary tumors in engineered mouse models bearing mutation in cell cycle master regulator genes, such as p27Kip1 and RB." (PMID 31487906, 2019). "Recent studies have shown that MEG3 inhibits pituitary tumor invasiveness through the MIR-376B-3P/HMGA2 axis." (PMID 38827318, 2024). "LncRNA RPSAP52 is found to upregulate HMGA2 via functioning as sponges of miR-16, miR-15b, and miR-15a in pituitary tumor." (PMID 35322746, 2022). "The overexpression of HMGA2 protein is also positively correlated with pituitary tumor phenotype, and overexpression of Hmga2 in transgenic mice results in the development of PA." (PMID 33574795, 2020). "A correlation between aberrant DNA methylation and the expression level was also observed for HMGA2, which plays an important role in the pathogenesis of pituitary tumors." (PMID 31731486, 2019). "Both the obtained double mutant mice (Hmga2/T;p27-KO and Hmga2/T;Cdk4R24C) displayed a significantly earlier onset of more aggressive pituitary tumors, with increased features of malignancies such as the upregulation of Ki-67 and a boosted number of mitoses." (PMID 31487906, 2019). "For example, miR-98 and miR-23b are involved in tumorigenesis of pituitary tumors and are down-regulated in GH tumors compared to normal pituitary samples and can directly inhibit HMGA2 expression." (PMID 26322309, 2015). "Increased Hmga2 expression or Hmga2 gene amplification initiate pituitary tumour development, and increased Hmga2 expression is found in several tumour types." (PMID 20976144, 2010). "Overexpressing Hmga2 induces pituitary tumours in mice by binding to and inhibiting retinoblastoma protein, a tumour suppressor." (PMID 20668695, 2010). "Conversely, an increase in E2F "free" DNA binding was always observed in pituitaries from single mutant HMGA2 mice even before the appearance of the pituitary tumour." (PMID 16914062, 2006). "In fact, the adenoma was diagnosed in only 25% of double mutant mice in respect to HMGA2 transgenic mice which all developed pituitary tumors." (PMID 16914062, 2006). "Therefore, the HMGA2 transgenic mouse model of pituitary tumorigenesis exhibits several analogies with human PitNETs where there is a female preponderance in pituitary tumor incidence with an earlier onset in female compared to male patients." (PMID 31487906, 2019).
esophageal squamous cell carcinoma (17 papers, 2016 to 2025). Esophageal squamous cell carcinoma (ESCC) is a type of esophageal carcinoma (EC) that can affect any part of the esophagus, but is usually located in the upper or middle third. "AKT also phosphorylates the acetyltransferase p300/CBP-associated factor (PCAF) and increases its acetylation on high-mobility group AT-hook 2 (HMGA2) at lysine 26 (K26) for esophageal squamous cell carcinoma growth." (PMID 35659740, 2022). "For example, circ-0006948 directly binds to miR-490-3p, which targets the 3′UTR of the oncogene high mobility group protein A2 (HMGA2) in esophageal squamous cell carcinoma (ESCC)." (PMID 33413401, 2021). "MiR-125b-5p also inhibited cell proliferation, migration, and invasion of esophageal squamous cell carcinoma partially by downregulating HMGA2." (PMID 34439740, 2021). "LncRNA ZEB2-AS1, through the miR-574-3p/HMGA2 axis, promotes the proliferation, migration, and invasion of esophageal squamous cell carcinoma cells." (PMID 34193130, 2021). "Circ_0006948 is a sponge of miR-490 in esophageal squamous cell carcinoma cells, and it upregulates the expression of oncogene HMGA2 to induce EMT by sequestering miR-490." (PMID 34055896, 2021). "In addition, a report has been illustrated that miR-490-3p suppressed the multiplication and metastasis of esophageal squamous cell carcinoma via modulation of HMGA2." (PMID 31920461, 2020). "For instance, Hsa-circ-10006948 drives the advancement of esophageal squamous cell carcinoma (ESCC) and triggers epithelial-mesenchymal transition by orchestrating the miR-490-3p/HMGA2 axis." (PMID 39591457, 2024). "The HMGA2 protein is a non-histone chromatin factor involved in DNA repair, aggressiveness of esophageal squamous cell carcinoma, epithelial-to-mesenchymal transition (EMT) process, and the up-regulation of EMT-related genes such as TGF-beta, SNAIL1, SLUG, MMP2, and MMP9 in RMS patients." (PMID 36139434, 2022).
oral squamous cell carcinoma (17 papers, 2007 to 2025). "A recent publication reported that suppressing Let-7 increased Oct4 and Sox2 expression in CSC-like oral squamous cell carcinoma (OSCC) by targeting ARID3B and HMGA2, which directly interact with Oct4 and Sox2." (PMID 26983719, 2016).